NSF (N-ethylmaleimide sensitive factor, vesicle fusing ATPase)
Description:
Required for vesicle-mediated transport. Catalyzes the fusion of transport vesicles within the Golgi cisternae. Is also required for transport from the endoplasmic reticulum to the Golgi stack. Seems to function as a fusion protein required for the delivery of cargo proteins to all compartments of the Golgi stack independent of vesicle origin. Interaction with AMPAR subunit GRIA2 leads to influence GRIA2 membrane cycling (By similarity).
Synonyms: SKD2; SEC18; DEE96
Tractability: Antibody: its Gene Ontology location is reachable by antibodies, with high confidence. PROTAC: ubiquitination databases record sites on it; its protein half-life has been measured.
Target class: Ion channel; Other ion channel; Vesicle fusion pores
Gene: Protein-coding gene on chromosome 17 (46,590,669 to 46,757,679, forward strand). Ensembl gene ENSG00000073969.
Subcellular location: Cytoplasm
Subcellular location (Human Protein Atlas): Cytosol; Golgi apparatus; Acrosome; End piece; Equatorial segment; Mid piece; Principal piece
Pathways (Reactome):
Vesicle-mediated transport: COPI-dependent Golgi-to-ER retrograde traffic; COPI-mediated anterograde transport; COPII-mediated vesicle transport; Intra-Golgi traffic; Retrograde transport at the Trans-Golgi-Network
Neuronal System: Trafficking of GluR2-containing AMPA receptors
Gene Ontology:
Molecular function: ionotropic glutamate receptor binding; PDZ domain binding; protein binding; protein-containing complex binding; ATP hydrolysis activity; ATP-dependent protein disaggregase activity; protein kinase binding; SNARE binding; syntaxin-1 binding; ATP binding
Biological process: intracellular protein transport; positive regulation of protein catabolic process; positive regulation of receptor recycling; endosomal vesicle fusion; exocytosis; Golgi to plasma membrane protein transport; intra-Golgi vesicle-mediated transport; regulation of exocytosis; SNARE complex disassembly; vesicle-mediated transport
Cellular component: cytosol; lysosomal membrane; plasma membrane; dendritic shaft; GABA-ergic synapse; Golgi stack; postsynaptic specialization, intracellular component; cytoplasm
Genetic constraint (gnomAD): Loss-of-function variants: 7 observed, 30.97 expected, observed/expected ratio (o/e) 0.23, 90% interval 0.13 to 0.43. The upper end of that interval is the gene's LOEUF score, 0.43, which puts it in group 1 of 6, group 1 being the genes least tolerant of losing a copy. Missense variants: 187 observed, 345.34 expected, observed/expected ratio (o/e) 0.54, 90% interval 0.48 to 0.61. Synonymous variants: 88 observed, 115.31 expected, observed/expected ratio (o/e) 0.76, 90% interval 0.64 to 0.91.
Homologues: Orthologues: chimpanzee NSF (99% identical), macaque NSF (99% identical), rabbit NSF (99% identical), dog NSF (99% identical), mouse Nsf (98% identical), rat Nsf (98% identical), guinea pig Nsf (97% identical), pig NSF (94% identical), tropical clawed frog nsf (91% identical), zebrafish nsfa (86% identical), zebrafish nsfb (82% identical), Drosophila melanogaster Nsf2 (63% identical), and 3 more.
Diseases named in the same sentence as NSF in open-access papers:
NSF is named in the same sentence as 51 diseases in open-access papers, as found by Europe PMC text mining. Sharing a sentence is not in itself a finding about the gene and the disease. The quoted sentences say what the papers report.
Parkinson disease (9 papers, 2013 to 2024). A progressive degenerative disorder of the central nervous system characterized by loss of dopamine producing neurons in the substantia nigra and the presence of Lewy bodies in the substantia nigra and locus coeruleus. "These multivariate ASD associations mapped to genes, including MAPT and NSF which are known to involved in biological pathways linked to neural disorders such as infantile epilepsy and Parkinson’s Disease." (PMID 39696186, 2024). "The common LRRK2 mutation G2019S enhances NSF kinase activity, potentially disrupting SV dynamics through abnormal phosphorylation of NSF and contributing to the manifestation of Parkinson’s symptoms." (PMID 39498393, 2024). "Variation in this region has been associated with Parkinson's disease (MAPT, PLEKHM1, NSF, c17orf69) progressive supranuclear palsy (MAPT), celiac disease (WNT3), bone mineral density (CRHR1) (NHGRI GWAS catalog) and intracranial volume." (PMID 23544013, 2013). "Meanwhile, six genes near MAPT in chromosome 17 including MAPT-AS1, SPPL2C, CRHR1, KANSL1, NSF, and WNT3 have been identified as risk genes by earlier GWAS for Parkinson’s disease, another common neurodegenerative disorder which might present clinical symptoms of FTD." (PMID 35509074, 2022). "Given that the most common Parkinson’s disease LRRK2 G2019S mutation displays increased kinase activity, our results suggest that mutant LRRK2 may impair synaptic vesicle dynamics via aberrant phosphorylation of NSF." (PMID 26758690, 2016).
schizophrenia (6 papers, 2012 to 2024). A major psychotic disorder characterized by abnormalities in the perception or expression of reality. "The NSF gene has also been linked with cocaine dependence and schizophrenia." (PMID 28775826, 2017). "Many genes that were found in this analysis, including CRHR1, ARL17A, NSF, and OGFOD2, have been implicated in previous GWAS of regional brain volumes, and have also been linked to brain disorders, including epilepsy, schizophrenia, and brain cancer." (PMID 39269986, 2024). "NSF is known to be involved in PD whereas KPNA1 is known to be involved in several neurological disorders including autism and schizophrenia." (PMID 28899360, 2017).
breast carcinoma (5 papers, 2014 to 2025). "Among them, 18 genes were essential for cancer cell proliferation, such as NSF for breast cancer, CCND1 for renal cell cancer, DHX16 for lung cancer, CDC27 for ovarian cancer, and CTDP1 for prostate cancer." (PMID 39025880, 2024). "In this study, by integrating CRISPR-CAS9 functional genomics (DEPMAP database) and TCGA multi-omics data, seven key genes (CDK7, CLTC, COPB2, CRNKL1, GSPT1, NSF and PSMD12) that are closely related to the proliferation and prognosis of breast cancer were systematically identified." (PMID 40657358, 2025). "Consequently, we identified five putative breast cancer RNA-binding proteins (PUF60, TFRC, KPNB1, NSF, and SF3A3) showing strong tumorigenic characteristics." (PMID 35453681, 2022). "Thus, based on their tumorigenic characteristics presented in this study and their roles in other cancer types, we identified five new putative breast cancer RBPs: PUF60, TFRC, KPNB1, NSF, and SF3A3." (PMID 35453681, 2022). "Of the out-of-frame validated chimeras, we identified recurrent expressed chimeric transcripts involving CDK12 (2.7%) and RAE1 (1%), and DNA rearrangements involving C17ORF57 (0.5%), NSF (0.5%), USH2A (0.5%), and LASP1 (1%) from unselected breast cancers in external datasets 12,15–17,41–43." (PMID 24395524, 2014). "CDK12, LASP1, RAE1, C17orf57, NSF, and USH2A were partners of out-of-frame, but not in-frame, fusion genes here and in other massively parallel sequencing analyses of breast cancers 12,15–17,41–43." (PMID 24395524, 2014).
COVID-19 (4 papers, 2021 to 2024). A disease caused by infection with severe acute respiratory syndrome coronavirus 2. "NSF was identified as a potential causal protein decreasing the risk of hospitalized COVID-19." (PMID 40303168, 2024). "Although, little is available about the relationship of NSF and COVID-19 in literature, one possible mechanism could be through α-SNAP, which reduces COVID-19 infection in cells and is an adaptor to NSF." (PMID 40303168, 2024).
epilepsy (3 papers, 2019 to 2024). A brain disorder characterized by episodes of abnormally increased neuronal discharge resulting in transient episodes of sensory or motor neurological dysfunction, or psychic dysfunction. "Screening for epilepsy-related genes has revealed a correlation between the NSF gene and the occurrence of spontaneous seizures." (PMID 39498393, 2024). "In an animal model of epilepsy induced by kainic acid, researchers observed a downregulation of NSF mRNA and protein expression in the hippocampal CA1 region following spontaneous seizures." (PMID 39498393, 2024). "Nonetheless, the observation that both flies with abnormal function in comt and infants with abnormal function in NSF exhibited epileptic phenotype illustrates that two orthologs (comt and NSF) in the two different species are related to the abnormal electrical discharges and epilepsy phenotype." (PMID 31675180, 2019). "Although the paralytic phenotype in flies does not prove but suggests that NSF dysfunction causes the epilepsy phenotype, we could not determine which mechanisms, that is, neurogenesis and/or neuroprotection, of the NSF are relevant to the patients' epileptic phenotype." (PMID 31675180, 2019).
ovarian carcinoma (3 papers, 2020 to 2024). A malignant neoplasm originating from the surface ovarian epithelium. "The association between PD and ovarian cancer was mostly driven by rs183211 located in an intron of the NSF gene (17q21.31)." (PMID 36788297, 2023).
autism (2 papers, 2017 to 2025). Persistent deficits in social interaction and communication and interaction as well as a markedly restricted repertoire of activity and interest as well as repetitive patterns of behavior. "A further protein involved in synaptic vesicular function downregulated in adults with autism was N-ethylmaleimide sensitive factor protein (NSF)." (PMID 40779003, 2025).
cataract (2 papers, 2010 to 2024). Partial or complete opacity of the crystalline lens of one or both eyes that decreases visual acuity and eventually results in blindness. "Follow-up analysis of the shared loci implicates candidate genes QKI, STK17A, TYR, NSF, and TCF4 likely contribute to the pathophysiology of cataracts and hearing difficulties." (PMID 38632618, 2024).
idiopathic pulmonary fibrosis (2 papers, 2021 to 2022). Idiopathic pulmonary fibrosis (IPF) is a nonneoplastic pulmonary disease that is characterized by the formation of scar tissue within the lungs in the absence of any known cause. "Among the respiratory conditions, only idiopathic pulmonary fibrosis (IPF) and chronic alveoli lung disease had shared associations with the variants near genes MUC5B, CRHR1, and NSF." (PMID 35482673, 2022). "Among the respiratory conditions, only idiopathic pulmonary fibrosis (IPF) and chronic alveoli lung disease had associations with the variants near genes MUC5B, CRHR1, and NSF." (PMID 34642702, 2021).
Insulin resistance (2 papers, 2022 to 2025). Increased resistance towards insulin, that is, diminished effectiveness of insulin in reducing blood glucose levels. "These genes have been involved in insulin resistance and secretion (ATM, PTPRN2, PSMD10, and NSF), adipogenesis (SLC25A24 and PAX8), inflammatory processes (TNFRSF8 and SLIT3), and mitochondrial processes (PM20D1 and LCLAT1)." (PMID 36535927, 2022).
mental disorder (2 papers, 2017 to 2025). A disease that has its basis in the disruption of mental process. "Several genes, such as PES1, SPI1, and NSF, exhibit multiple significant associations across different traits, indicating their potential central roles in the genetic network influencing psychiatric disorders." (PMID 39905509, 2025).
brain ischemia (1 paper, 2020). Diminished or absent blood supply to the brain caused by obstruction (thrombosis or embolism) of an artery resulting in neurologic damage. "NSF binds to ASIC1a distal NT in a state-dependent fashion, exhibiting increased association under acidosis and brain ischemia." (PMID 31980622, 2020). "This argues for a critical role of ASIC1a in bridging the association between NSF and RIPK1 in response to brain ischemia." (PMID 31980622, 2020).
breast tumors (1 paper, 2021). "In addition, some of the DEPs identified in these signaling pathways were also differentially expressed between the male and female breast tumors, such as the ones encoded by CES1, CRYAB, NSF, PRKDC and SERPIND1 genes." (PMID 33656060, 2021).
dependence (1 paper, 2016). "In a previous study, our group identified an association between a quick transition from cocaine use to dependence and a risk haplotype (rs183211G-rs17698176T) in the NSF gene." (PMID 27498889, 2016).
developmental and epileptic encephalopathy (1 paper, 2023). An epilepsy associated with developmental impairment that may be due to either the underlying etiology or the superimposed epileptic activity, or both. "Recently, the association between pathogenic NSF variants and developmental and epileptic encephalopathy (DEE) was reported; however, the molecular pathomechanism of NSF-related DEE remains unclear." (PMID 36645181, 2023).
Epileptic encephalopathy (1 paper, 2019). A condition in which epileptiform abnormalities are believed to contribute to the progressive disturbance in cerebral function. "Here, we describe two patients with de novo pathogenic variants in NSF with early infantile epileptic encephalopathy, to demonstrate that pathogenic variants of NSF cause the monogenic epileptic phenotype in humans." (PMID 31675180, 2019). "We conclude that de novo heterozygous mutations in the NSF cause early infantile epileptic encephalopathy." (PMID 31675180, 2019). "In the present report, we, for the first time, document epileptic encephalopathy of infantile onset caused by de novo heterozygous pathogenic variants in the gene encoding NSF, a molecule that is critical for intracellular vesicle transport and membrane fusion." (PMID 31675180, 2019). "De novo heterozygous mutations in the NSF gene cause early infantile epileptic encephalopathy." (PMID 31675180, 2019).
Hydrocephalus (1 paper, 2025). Hydrocephalus is an active distension of the ventricular system of the brain resulting from inadequate passage of CSF from its point of production within the cerebral ventricles to its point of absorption into the systemic circulation. "When mutations in NSF in relation to hydrocephalus were searched using PubMed, several articles were obtained in which a mutation in alpha-SNAP was correlated to hydrocephalus in hyh mice (hydrocephalus with hop gait)." (PMID 40430021, 2025).
ischemic stroke (1 paper, 2024). A stroke disorder caused by obstruction of blood flow to the brain, due to thrombotic (local blood clot formation) or embolic (due to a blood clot or other material traveling from another site) event. "However, the mechanism underlying the sequential recruitment of receptor-interacting protein kinase 1 (RIPK1) and N-ethylmaleimide-sensitive fusion ATPase (NSF) in initiating necroptosis remains poorly understood, and the role of NSF in ischemic stroke is a subject of controversy." (PMID 38919602, 2024). "Moreover, the involvement of NSF in ischemic stroke remains controversial." (PMID 38919602, 2024). "However, the precise mechanism by which NSF and RIPK1 cooperate to initiate necroptosis remains unclear, and the role of NSF in ischemic stroke is a subject of controversy." (PMID 38919602, 2024).
myopia (1 paper, 2018). "Specifically, the present findings are in agreement with previous reports of up-regulation of the NSF protein during lens-induced myopia in mouse, and up-regulation of the GABAA receptor mRNA and protein and increased retinal GABA content during lens-induced myopia in guinea pigs." (PMID 30157773, 2018).
Sepsis (1 paper, 2016). Sepsis is defined as life-threatening organ dysfunction caused by a dysregulated host response to infection. "In conclusion, the data suggest a possible novel therapeutic approach in sepsis/ARDS by targeting NSF, a trafficking mediator molecule involved in the secretion of inflammatory mediators from endothelial cells and in the maintenance of vascular tone." (PMID 27355324, 2016).
cancer (6 papers, 2015 to 2024). A tumor composed of atypical neoplastic, often pleomorphic cells that invade other tissues. "These putative BC progressor RBPs (PUF60, TFRC, KPNB1, NSF, and SF3A3) were integrated into a disease gene network to shed light on their molecular and cellular functions in cancer." (PMID 35453681, 2022). "To better understand the cellular functions of these prioritized RBPs (TFRC, KPNB1, PUF60, NSF, and SF3A3) in cancer, we next interrogated the HumanNet v2." (PMID 35453681, 2022). "Interestingly, NSF, SF3A3, PRPF3, and MAGOHB have never been studied in cancer." (PMID 35453681, 2022). "Interestingly, NSF and SF3A3 have never been studied in cancer." (PMID 35453681, 2022).
neurological disorders (6 papers, 2017 to 2025). "The dysfunction of NSF-mediated trafficking of these receptors is associated with several neurological disorders." (PMID 39498393, 2024). "NSF protein functionally important for the delivery of cargo proteins to all compartment of the Golgi stack and highly associated with neoplasm and nervous system diseases." (PMID 34918006, 2022). "Therefore, investigating the association between the NSF protein and neurological disorders helps unravel the pathophysiological mechanisms of these diseases and provides a theoretical basis for developing novel therapeutic strategies." (PMID 39498393, 2024). "This review aims to provide a comprehensive overview of the diverse roles of NSF in neuronal physiology, elucidate its mechanisms of action at various stages of synaptic function, and explore its correlations with different neurological diseases." (PMID 39498393, 2024). "The illustration shows how NSF is involved in various neurological disorders by regulating and controlling key receptors within synaptic structures." (PMID 39498393, 2024). "The ATPase N-ethylmaleimide-sensitive factor (NSF), known for disassembling SNARE complexes, plays key roles in neurotransmitter release, neurotransmitter (AMPA, GABA, dopamine) receptor trafficking, and synaptic plasticity, and its dysfunction or mutation is linked to neurological disorders." (PMID 40894625, 2025). "Also, 59 unique proteins were associated with AD, and 10 of them (17%) showed an association with AD and an additional neurological disease (CTF1, NSF and PRSS53 with PD; SIGLEC9 with ALS; CR1, CTSH, PARP1 and PVR with MS; LRRC37A2 with both PD and ALS; and IDUA with PD, ALS and MS)." (PMID 40037332, 2025).
tumor (4 papers, 2022 to 2024). "In comparison, the expression of GNB4 and NSF in tumor tissues was significantly lower than that in normal tissues, suggesting that these key genes play an essential role in the occurrence and development of ccRCC." (PMID 36237326, 2022).
infection (2 papers, 2014). The state of being infected such as from the introduction of a foreign agent such as serum, vaccine, antigenic substance or organism. "Silencing of NSF, required for transport from early to late endosomes, or of the HOPS subunits VPS11 and VPS41, which are involved in late endosome to lysosome maturation, all resulted in severely reduced MHV infection (turquoise and light green, respectively)." (PMID 25375324, 2014).
neurodegenerative disease (2 papers, 2022 to 2025). A disorder of the central nervous system characterized by gradual and progressive loss of neural tissue and neurologic function. "Other genes such as SPI1, LRRC37A, NSF, and TCTA have also been reported to have effect on neurodegenerative diseases." (PMID 39905509, 2025).
NSF also shares sentences with these, for which no sentence is quoted: cognitive decline (3 papers); Alzheimer disease (2); amnesia (1); amyotrophic lateral sclerosis (1); Anxiety (1); bacterial infections (1); brain cancer (1); brain disorder (1); celiac disease (1); cocaine dependence (1); dementia (1); diphtheria (1); dyslexia (1); endometrial cancer (1); hypothyroidism (1); infant botulism (1); infantile epilepsy (1); lung carcinoma (1); nematode infection (1); oral cancer (1); Parkinson’s (1); primary bone cancer (1); progressive supranuclear palsy (1); prostate carcinoma (1); renal cell cancer (1); tetanus (1).